IL6 (interleukin 6)
Diseases named in the same sentence as IL6 in open-access papers (continued):
Sharing a sentence is not in itself a finding about the gene and the disease.
metabolic syndrome (continued). "In fact, it is well known that chronic inflammation states may induce dyslipidemia through the action of proinflammatory cytokines such as tumor necrosis factor- α or interleukin-6 perpetuating this visceral fat accumulation." (PMID 37764769, 2023). "Additionally, a nutritional study with ACYs in participants with dyslipidemia showed that supplementation with more of these polyphenols exerts a stronger effect on the reductions in IL-6 and TBARS in the serum." (PMID 36678224, 2023). "On the contrary, elevated IL-6 levels could only be observed in male patients with metabolic syndrome and were negatively correlated with their high-density lipoprotein levels." (PMID 37370004, 2023). "In addition, we provide evidence supporting the role of IL-10 as a counteracting response to IL-6 mediated inflammation, thereby preventing development of metabolic syndrome." (PMID 35135482, 2022). "High IL-6 combined with low IL-10 levels were associated with risk of metabolic syndrome (OR 3.83, 95%CI 1.07–13.75), however not statistically significantly after adjustment." (PMID 35135482, 2022). "The objective of this study was to determine the relationship between prevalence of dyslipidemia and measured changes in the levels of proinflammatory cytokines (IL-6, TNF-a, and MCP-1), thiobarbituric acid-reactant substances (TBARS), and serum total antioxidant capacity (TAC) in serum samples." (PMID 36032093, 2022). "During metabolic syndrome, these inflammatory cells secrete massive amounts of proinflammatory cytokines, as Interferon γ (IFNγ), Interleukin 6 (IL-6), and TNFα, lipid mediators, as Leukotriene B4 (LTB4), and chemokines, as Monocyte Chemoattractant Protein-1 (MCP1)." (PMID 35164764, 2022). "Among the components of metabolic syndrome, abdominal obesity is characterized by a chronic low-grade systemic inflammation, involving increased plasma pro-inflammatory cytokine levels such as interleukin-6 (IL-6) and tumor necrosis factor-alpha (TNF-α)." (PMID 35807489, 2022). "Although IL-6 levels were associated with waist circumference, BMI, HbA1c, and insulin levels the association with metabolic syndrome was not statistically significant." (PMID 35135482, 2022). "Il-6 was also upregulated in the livers of female WT mice compared with male WT mice, which fits the hypothesis that upregulation of Il-6 in the liver is a protective factor in response to HFD-induced metabolic syndrome." (PMID 36013467, 2022). "However, drinking alcohol during exercise exacerbates dyslipidemia and oxidative stress, with hepatocyte IL-6–p47phox downregulated." (PMID 35455983, 2022). "S-TMAO (microbial-derived choline metabolite) levels were dose-dependent associated with CVD outcomes and other indicators such as serum cholesterol, glycaemic indices (HbA1c, fasting plasma glucose), inflammation biomarkers (IL-6, CRP), overall cardiovascular risk, and metabolic syndrome." (PMID 36558520, 2022). "While TNF‐α appears to be more involved in the mechanism and progression of the metabolic syndrome (e.g., reduced insulin sensitivity through an increase in JNK1/2 activation), IL‐6 is likely only a marker of metabolic syndrome since it has been shown to increase lipolysis and fat oxidation." (PMID 35312183, 2022). "To fill this gap, in this follow-up study we set out to explore the difference of hepcidin, iron metabolism markers and IL-6 between obese and not obese adolescents, and to identify associations with inflammation, atherogenic dyslipidemia, IR and visceral fat." (PMID 34065056, 2021). "Recently, studies had shown that vitamin D supplementation could reduce inflammation biomarkers [ie interleukin-6 (IL-6) levels] in adults with metabolic syndrome." (PMID 35250848, 2021). "In the present study we set out to expand these findings by exploring the status of IL-6 as a potent adipokine from visceral fat that induces hepatic IR and dyslipidemia, since it is known that it may affect iron metabolism as reported by others." (PMID 34065056, 2021).
metabolic syndrome (continued). "According to the literature, in supracoronary aortic banding plus metabolic syndrome animals, reducing IL-6, either by anti-IL-6 antibody or metformin treatment, could reverse pulmonary vascular remodeling." (PMID 33505509, 2021). "Furthermore, IL-6 levels were significantly decreased in subjects with dyslipidemia (SMD = -0.34; 95% CI: -0.59, -0.10; P = 0.006; I 2 = 0%)." (PMID 34513905, 2021). "Compared to patients with non-PolyVD and IL-6 < 2.64 pg/ml (group 1), patients with PolyVD and IL-6 ≥ 2.64 pg/ml (group 4) were older, had more females, smoked and drank less, and had higher proportions of hypertension, DM, dyslipidemia, AF, previous IS, infection, NIHSS score, and medication usage." (PMID 33927687, 2021). "Thus, the present study aimed to examine, for the first time, the combined effects of FG and ω-3 PUFA on dyslipidemia, transaminases, interleukin-6, and oxidative in pre-obese rats." (PMID 33557198, 2021). "Furthermore, the TNF-α and IL-6 levels were decreased in the CCL4 antibody-treated group compared with those in the IgG-treated metabolic syndrome group." (PMID 33968046, 2021). "Among individuals with (n = 44) and without (n = 83) metabolic syndrome, progranulin levels were associated with higher concentrations of C-reactive protein (CRP), IL-6, number of metabolic syndrome components, and increased intima-media thickness in individuals without metabolic syndrome." (PMID 31940832, 2020). "In addition, a meta-analysis study demonstrated a decrease in C-reactive protein, tumor necrosis factor-α, interleukin-6, and interleukin-1 levels in statin users with metabolic syndrome and related diseases." (PMID 33202921, 2020). "Interestingly, the prevalence of metabolic syndrome and IL6, a more robust marker of low-grade, chronic inflammation was also higher in the presence of hs-CRP levels ≥3 mg/l." (PMID 32514365, 2020). "Furthermore, an AMPK activator metformin ameliorates systemic inflammation through inhibiting C-reactive protein and IL-6 in patients with metabolic syndrome." (PMID 32954935, 2020). "IL-6 also promotes the expression of adhesion molecules by endothelial cells and activates the local renin-angiotensin system, whose activation contributes to metabolic syndrome development." (PMID 32466598, 2020). "It is hypothesized that increasing serum fatty acids associated with metabolic syndrome stimulate TLR4 leading to increased serum levels of TNF-alpha, IL-1B, and IL-6." (PMID 33072103, 2020). "In situations of inflammation, common in metabolic syndrome, a variety of mediators (including tumor necrosis factor-α, interleukin 6, and interleukin 10) could have an impact on NF-κB pathway." (PMID 30945110, 2019). "Similarly, in adults with features of metabolic syndrome, the consumption of 400 g/d of whole bilberries for 8 weeks reduced an index of inflammation calculated from the sum of the Z scores for hsCRP, Interleukin-6 (IL-6), IL-12 and lipopolysaccharides." (PMID 29743826, 2018). "In addition, higher TSH and IL-6 concentrations were detected in metabolic syndrome while AITD was reported to be associated with higher TSH and IL-6 levels as well." (PMID 30405316, 2018). "This may be correlated with the fact that elevated serum levels of IL-6 are recognized as an early and representative marker in metabolic syndrome pathogenesis." (PMID 30356025, 2018). "The potential link between IL-6 and dyslipidemia has been demonstrated by several studies." (PMID 30134607, 2018). "Huanglian-Wendan decoction is reported to reduce serum IL-6 levels in metabolic syndrome of rats." (PMID 29853787, 2018). "Since serum FA concentration is one of the major determinants of cardiac FA uptake rate, dyslipidemia secondary to IL-6 abnormality is likely to facilitate excessive FA import which may result in myocardial lipid accumulation and lipotoxicity." (PMID 30134607, 2018).
metabolic syndrome (continued). "The mechanism to accelerate the favorable impact of IL-6 on metabolic processes is currently being investigated—these studies may lead to a new treatment method for metabolic syndrome and type 2 DM." (PMID 29694426, 2018). "When hsCRP or IL-6 were also added to the models, estimates of metabolic syndrome factors were reduced, indicating that these pro-inflammatory biomarkers could explain part of the association between CR-fitness and factors of the metabolic syndrome." (PMID 29590212, 2018). "IL-6 and leptin activity in hypothalamus could explain co-occurrence of schizophrenia and metabolic syndrome." (PMID 29163240, 2017). ": According to the findings of this study, it can be concluded that GSE withits effects on serum TC, LDL-C and IL-6 could reduce the effects of dyslipidemia andinflammation in PCOS rats and improve systemic symptoms of PCOS." (PMID 28868839, 2017). "We hypothesize that in the metabolic syndrome, reduced myocyte perfusion decreases intracellular glycogen and upregulates myocyte expression of IL-6." (PMID 29435395, 2017). "Milk from diabetic mothers may also contain more inflammatory cytokines (e.g. TNF-α, IL-6) which mimic signalling pathways characteristic of dysfunctional adipocytes of metabolic syndrome." (PMID 26415764, 2017). "However, serum IL-6 levels are mainly affected not only by the metabolic syndrome but also by age and smoking status." (PMID 26366318, 2015). "Modelling indicates that the significant predictors of CRP levels were biomarkers of the metabolic syndrome while the significant predictors of IL-6 levels were age and plasma triglycerides among former smokers and the numbers of smoked packs of cigarettes per year among smokers." (PMID 26366318, 2015). "PCOS, as one of the diseases that is associated with metabolic syndrome, also may have changes in inflammation factors such as C3,CRP, interleukin-6, tumor necrosis factor-a, and lipid profiles." (PMID 25904961, 2015). "In this paper we briefly describe the pathophysiologic role of four important adipokines (adiponectin, leptin, TNF-α, and IL-6) in the metabolic syndrome and review some of the clinical trials that monitored these adipokines as a clinical outcome before and after exercise." (PMID 24563869, 2014). "Controlling the release and activity of at least two cytokines, namely, TNF-α and IL-6, could contribute to the natural protective effects of physical activity in the metabolic syndrome." (PMID 24563869, 2014). "Although these observations suggest a potential role for IL-6 in metabolic syndrome, the potential activation of intracellular signaling pathways by this cytokine remains unclear." (PMID 23365487, 2013). "Inflammation and atherogenic dyslipidemia may be linked by the fact that TNF alpha and IL-6 stimulate lipolysis and increase the flow of free fatty acids to the liver." (PMID 23526980, 2013). "First, markers of the inflammatory response such as tumor necrosis factor-alpha (TNF-alpha), interleukin-1β (IL-1β), interleukin 6 (IL-6), plasminogen activator inhibitor 1 (PAI1), and C-reactive protein (CRP) are strongly associated with features of the metabolic syndrome in humans." (PMID 22479352, 2012). "Moreover, Mediterranean-like diet was shown to reduce levels of CRP, IL-6 and IL-18 in a middle-aged population with the metabolic syndrome." (PMID 20331890, 2010). "Sequence variation of the IL6 gene (NM_000600.1) is related to metabolic syndrome in older males." (PMID 19774229, 2009). "Finally, in patients with metabolic syndrome who consumed black raspberry for 12 saw significant decreases in total serum cholesterol levels and inflammatory cytokines, including IL-6, TNF-α, CRP, sICAM-1, and sVCAM-1, ultimately improving vascular endothelial function." (PMID 41156509, 2025).
metabolic syndrome (continued). "The resulting dyslipidemia and accumulation of LDLs can, in turn, induce inflammasome activation and the release of pro-inflammatory cytokines such as IL-1 and IL-6, promoting a systemic inflammatory state that could drive the pathophysiology of both dyslipidemia and steatotic liver disease." (PMID 41441037, 2025). "Moreover, IL-6 can stimulate lipolysis and fat oxidation in humans without causing hypertriglyceridemia, which can have significant benefits for patients with metabolic syndrome." (PMID 41141350, 2025). "Therefore, IL-6 leads to several metabolic disorders including metabolic syndrome and T2D." (PMID 40003433, 2025). "Additionally, a significant relationship was found between isoleucine and IL-6 in patients with metabolic syndrome, suggesting that isoleucine may be a potential predictive biomarker for the pro-inflammatory state of metabolic syndrome." (PMID 39822378, 2024). "Likewise, in patients with geriatric cachexia, a complex metabolic syndrome characterized by excessive loss of body mass, pro-inflammatory markers such as TNF-α, IL-1, and IL-6 have been linked to symptoms such as decreased gastric motility and emptying, nausea, and vomiting." (PMID 38170327, 2024). "Additionally, in the environment of dyslipidemia, the secretion of pro-inflammatory cytokines, such as IL-6 is activated, and to counteract this, the secretion of CD-16 monocytes and TNF-alpha is also increased, creating an environment in which the inflammatory response is activated." (PMID 38201008, 2024). "Furthermore, the correlation of Treg% and IL-6 with dyslipidemia in pSS patients suggests that these markers may play a key role in the development of CHD and can serve as potential biomarkers for assessing inflammatory status in pSS patients." (PMID 39664378, 2024). "Metabolic syndrome (MetS), characterized by a cluster of metabolic dysregulations, such as abdominal obesity, hypertension, hyperglycemia, and dyslipidemia, leads to systemic low-grade inflammation primarily through the increased production of proinflammatory cytokines, such as IL-6, CRP, and TNF-α." (PMID 39452916, 2024). "In addition, ADIPOQ and IL-6 could consider cut-point nodes and suitable proteins in the pathomechanism of T2D and dyslipidemia." (PMID 37542207, 2023). "In addition, it has been noted that elevated IL-6 levels in schizophrenia may contribute to the occurrence of metabolic syndrome." (PMID 37370004, 2023). "Moreover, patients with psoriatic arthritis showed higher serum IL-6, TC, and LDL-C levels than patients with psoriasis alone, indicating that IL-6 might be related to dyslipidemia in patients with autoimmune disease." (PMID 37108210, 2023). "Interestingly, a combination of high IL-6 and low IL-10 levels was associated with an increased risk of metabolic syndrome, although not statistically significantly after adjusting for confounders." (PMID 35135482, 2022). "Pro-inflammatory cytokines, such as tumor necrosis factor alpha (TNF-α) or interleukin-6 (IL-6), are elevated in the serum of metabolic syndrome patients, and an increased level of pro-inflammatory cytokines may play an essential role in the pathogenesis of the syndrome." (PMID 35888020, 2022). "IL-6 and its soluble receptors, sIL-6R and soluble gp130 receptors were positively associated with serological markers of endothelial function (E-selectin, I-CAM-1, V-CAM-1) and inversely with pulse wave propagation time, a marker of arterial stiffness in patients with metabolic syndrome." (PMID 34202323, 2021). "Elevated IL6 expression in CA patients may imply an initial hepatic inflammation due to HBV/HCV that may have progressed to liver cancer; while the increased levels of CYP2D6 in AS may be due to another underlying problem like alcohol or metabolic syndrome." (PMID 34597305, 2021).
metabolic syndrome (continued). "Studies based on pre-diagnostic CRP levels have shown that other (BMI, IL-6 in healthy but not overweight men, leukocytes, metabolic syndrome components) or multiple etiologies of chronic inflammation correlate with increased prostate cancer risk, but often not CRP individually." (PMID 34926085, 2021). "In this cross-sectional study of 29 obese adolescents and 30 control subjects, we explored the difference of hepcidin, iron metabolism markers and IL-6 between obese and non-obese adolescents, and identified associations with inflammation, atherogenic dyslipidemia and IR." (PMID 34065056, 2021). "Consistent with the dysregulation in adipokine levels, metabolic syndrome has been associated an aggravation in inflammation, and this state that is characterized by increased pro-inflammatory cytokines and acute phase reactants such as CRP, IL-6, and tumor necrosis factor alpha (TNF-α)." (PMID 32375340, 2020). "TNF-α and interleukin-6 (IL-6), known as inflammatory cytokines, cause chronic low-grade inflammation, which, in turn, may trigger other chronic pathophysiological conditions such as T2DM, metabolic syndrome, and heart disease." (PMID 33266423, 2020). "However, other diagnostic criteria of MS (hypertension and/or dyslipidemia) or inflammation (elevated IL-6 levels) does not cause further increase in GV." (PMID 28163257, 2017). "However, other diagnostic criteria of MS (hypertension and/or dyslipidemia) or elevated IL-6 levels does not cause further increase in GV." (PMID 28163257, 2017). "Our finding that obese individuals who have met the diagnostic criteria for metabolic syndrome had higher mean levels of IL-1β, IL-6, and IL-15 in VAT than obese individuals without MS also supports this hypothesis." (PMID 26516848, 2015). "However the degree of improvement of HDL-particle (HDL-p) and ApoA1 levels was lower in those with high baseline CRP and IL-6, indicating a relationship between high chronic immune inflammation and an impaired ability to resolve dyslipidemia in chronic HIV infection." (PMID 24086545, 2013). "We also determined whether any age-related changes in serum ALT were explained by metabolic syndrome components, adiposity-related biomarkers including leptin, adiponectin, ghrelin and interleukin-6 (IL-6), or other markers of hepatic function (bilirubin, albumin, gamma glutamyl transferase [GGT])." (PMID 21170382, 2010). "Diabetic rats also showed dyslipidemia, liver dysfunction, increased oxidative stress (↓GSH, ↑MDA), and elevated inflammatory markers (TNF-α, il-6)." (PMID 41361213, 2025). "Their meta-analysis on patients with metabolic syndrome observed that berberine significantly reduced CRP by −1.54 mg/L, TNF-α by −1.02 pg/mL, and IL-6 by −1.17 pg/mL levels." (PMID 40006007, 2025). "Numerous patients with metabolic syndrome exhibit elevated inflammatory marker concentrations, including C-reactive protein (CRP), tumor necrosis factor-alpha (TNF-α), and interleukin-6 (IL-6)." (PMID 41245414, 2025). "Notably, salivary cytokines—such as interleukin-6 (IL-6), tumor necrosis factor-alpha (TNF-α), and interleukin-1β (IL-1β)—can be co-analyzed with SAA to assess inflammatory states associated with chronic stress, metabolic syndrome, or low-grade systemic inflammation." (PMID 40806495, 2025). "We therefore evaluated the inflammatory markers IL-6, TNF-α, hsCRP, and metabolic syndrome as potential indicators of ovarian aging and CVD." (PMID 40713717, 2025). "For instance, tadalafil has been shown to decrease IL-6 and TNF-α expression in rodent models of metabolic syndrome and pulmonary inflammation." (PMID 40806281, 2025). "For example, Heng et al7 found that administering 400 mg of TRF daily for 16 weeks resulted in a significant decrease in TC, LDL-C, HDL-C, IL-6, and tumor necrosis factor-alpha (TNF-α) in patients with metabolic syndrome." (PMID 38916919, 2025).